EGFR (epidermal growth factor receptor)
Diseases named in the same sentence as EGFR in open-access papers (continued):
Sharing a sentence is not in itself a finding about the gene and the disease.
neuroblastoma (continued). "Bioinformatic analysis showed that overall survival was far better in neuroblastoma patients bearing a tumor expressing high level of CD, irrespective of the level of EGFR expression." (PMID 35563171, 2022). "In neuroblastoma cells, UBE4B participates in lysosomal degradation of EGFR." (PMID 36440598, 2022). "Our findings encourage in vitro testing of the effects of resveratrol as adjuvant therapy for neuroblastomas low-expressing cathepsin D and not responding to the EGFR inhibitor gefitinib." (PMID 35563171, 2022). "Fe3O4@TiO2 nanoconjugates without the EGFR-targeting peptide tend to accumulate in cytoplasm of SK-N-AS and SK-N-DZ neuroblastoma cells." (PMID 34777621, 2021). "EGFR is often expressed in neuroblastoma, but there is no consensus on its role and prognostic impact." (PMID 30135355, 2018). "Altogether, these data indicate that activation of EGFR enhanced the expression of P2X7R in neuroblastoma cells lacking trophic support, being PI3K/Akt/PKCζ signaling pathway and Sp1 mediating this pro-survival outcome." (PMID 26687764, 2015). "EGFR and IGF-1R activation has been shown to increase cell proliferation, inhibit apoptosis, induce resistance to chemotherapy and increase Mycn protein levels in neuroblastoma." (PMID 24759734, 2014). "DTCs from neuroblastoma patient samples were isolated based on expression of the cell surface marker GD2, while spiked cell line tumor cells were detected and captured by labeling for GD2, HER2 (breast), EGFR (NSCLC), and EpCAM (colon)." (PMID 25133137, 2014). "To confirm the tyrosine kinase inhibitory property of GST, we treated human malignant neuroblastoma SK-N-BE2 and IMR-32 cell lines with increasing doses of GST and performed Western blotting for monitoring the changes in expression of EGFR at the protein level." (PMID 24205354, 2013). "Growth of LA-N-5 neuroblastoma cells as non-adherent, nestin positive, multi-potent tumorspheres was dependent upon γ-secretase and EGFR signaling, similar to neural stem cells." (PMID 19156211, 2009). "Furthermore, DpC succeeded in downregulating total EGFR and phosphorylation of its most prominent tyrosine residues through the involvement of NDRG1, a positive prognostic marker in neuroblastoma, which was markedly upregulated after thiosemicarbazone treatment." (PMID 35008802, 2021). "Not surprisingly, expression of EGFR was detected in all neuroblastoma cell lines examined." (PMID 31293052, 2019). "This analysis was performed in human neuroblastoma SH-SY5Y cells since human EGF ligand that we used for monitoring EGFR uptake and its lysosomal degradation could not be used in CHO cells." (PMID 27902765, 2016). "Here, we looked for the correlation between the MYCN, CTSD, EGFR and MAPK1 genes and checked the prognostic value of CTSD in the context of MYCN positive and negative neuroblastomas." (PMID 38611021, 2024). "Taken together, our data imply that PHLDA1 silencing enhances the EGF receptor signaling pathway, but the influence is unidirectional since neither EGFR activation, nor inhibition does not generate changes in the PHLDA1 level in shCtrl cells and IMR-32 neuroblastoma cells." (PMID 38495105, 2024). "However, PON does not affect neuroblastoma cells through the chimeric protein BCR-ABL, since it is not found in this pediatric malignancy, but rather through other TKs, such as FGFR1 or EGFR." (PMID 32962733, 2020). "Moreover, EGFR inhibition also reduced Akt phosphorylation induced by serum deprivation, indicating that EGFR activation is necessary to trigger PI3K/Akt signaling pathway and, consequently, to induce Sp1-dependent upregulation of P2X7R in neuroblastoma cells lacking trophic support." (PMID 26687764, 2015).
viral infection (115 papers, 2009 to 2026). "As EGFR is positively correlated with viral infection in hBMECs, the underlying specific mechanism needs to be further elucidated." (PMID 35847084, 2022). "The EGFR is mostly highly expressed and mutated as a result of toxic environmental stimuli, such as ultraviolet irradiation carcinogens and viral infection." (PMID 33273921, 2020). "Our prediction analysis showed enrichment for pathways associated with viral infection strategies (such as viral translation) and oncogenesis (such as Wnt signaling, EGFR signaling)." (PMID 31416416, 2019). "While there was a significant increase in the association of Rab 5 or 11 and EGFR between uninfected and infected cells, we did not observe a statistically significant change between WT and mutant virus infections." (PMID 27218650, 2016). "EGFR production has been linked to thrombosis risk and inflammatory markers, and it was previously shown that viral infections may induce EGFR signalling and promote a pro-inflammatory and pro-angiogenic response." (PMID 35938548, 2022). "Mechanistically, 4HCH targets the early stages of viral infection by binding to the epidermal growth factor receptor (EGFR) and inhibiting the EGFR/AKT/ERK1/2 signaling pathway, thereby suppressing viral replication." (PMID 40872743, 2025). "During the early stages of COVID-19 pathogenesis, EGFR is down-regulated, contributing to the progression and spread of the viral infection." (PMID 40371107, 2025). "Nevertheless, the relationship between viral infection (HPV, EBV) and EGFR mutations in NSCLC remains poorly defined." (PMID 41327362, 2025). "In conclusion, EGFR-Rac1 shows dynamic activation during early viral infection and exerts its main regulatory effects upon the RABV entry stage." (PMID 38809020, 2024). "Viral infection-induced FUT8 expression was dependent on EGFR, AKT, and SNAIL, as HCV-infection-induced upregulation of FUT8 mRNA levels and FUT8 promoter activation were attenuated in Huh7 cells after silencing EGFR, AKT, or SNAIL." (PMID 38253527, 2024). "Given that miR-191-5p can directly bind to porcine EGFR mRNA, we explored the role of EGFR in the host, particularly its function during viral infection." (PMID 39469460, 2024). "In early viral infection, the EGFR-Rac1-signaling pathway undergoes a biphasic change, which is first upregulated and subsequently downregulated, corresponding to the RABV entry-induced remodeling pattern of F-actin." (PMID 38809020, 2024). "CD8+ T cells were activated for 3 days at either 37 °C (act-37 °C) or at 39 °C (act-39 °C) and then transferred to 37 °C for viral infection (anti-EGFR CAR) and subsequent expansion." (PMID 38467616, 2024). "To further explore the role of miR-191-5p in modulating the effects of EGFR on viral infection and IFN-β expression, we overexpressed miR-191-5p before exposing PAMs to EGF stimulation." (PMID 39469460, 2024). "In this study, we report that SARS-CoV-2 aberrantly elevates mitochondrial bioenergetics and activates the EGFR-mediated cell survival signal cascade during the early stage of viral infection." (PMID 38734691, 2024). "By disrupting EGFR signaling, an environment conducive to viral infection is established, shedding light on a critical aspect of HEV infection: the infection-associated disturbance of innate immunity and the potential involvement of EGFR in this process." (PMID 38856640, 2024). "Despite the low overall activity, these derivatives outperformed known EGFR inhibitors like erlotinib and icotinib, highlighting their potential in targeting viral infections." (PMID 39683709, 2024). "The epidermal growth factor receptor (EGFR) has been proved to be one of the co-receptors involved in many viral infections and a key protein involved in the regulation of NHE3 activity in response to various pathological stimuli." (PMID 38029193, 2023).
viral infection (continued). "To further validate EGFR as a cofactor for viral infection and evaluate the EGFR-MAPK pathway as a potential therapeutic target to prevent infection, we analyzed the effect of MEKi treatment on authentic SARS-CoV-2 infection." (PMID 37402592, 2023). "These intricate functions rely on the precisely orchestrated regulation of EGFR activation, which can effectively toggle between various viral infection states, such as latency and reactivation, or profoundly affect discrete phases of the viral life cycle." (PMID 38136637, 2023). "Exploring the function of EGFR in viral infections can offer insights into the development of innovative antiviral strategies." (PMID 38136637, 2023). "In a recent study, most evidence supported the roles of EGFR in facilitating viral entry, replication, or escape from the host immune response in viral infections." (PMID 38136637, 2023). "It has been well documented that EGFR can act as one of the co-receptors involved in viral infection." (PMID 38029193, 2023). "Recent advancements in research have underscored the profound and multifaceted role of EGFR in viral infections, highlighting its involvement in viral entry, replication, and the subversion of host immune responses." (PMID 38136637, 2023). "We expect that further investigation of the role of EGFR in viral infections will not only enhance our understanding but also facilitate the development of innovative antiviral strategies." (PMID 38139259, 2023). "Since the invasion process of PEDV occurs early in the infection, it has been shown that viral infection can competitively exploit the endocytosis of EGFR and activate EGFR downstream signaling pathways to counteract the host’s antiviral response." (PMID 38029193, 2023). "The EGFR signaling pathway is activated in response to stress-induced signals such as viral infections." (PMID 38139259, 2023). "Considering all previous studies on different viruses and the current data on SARS-CoV-2, we aimed at dissecting the role of EGFR–RAS–MAPK axis in viral infection." (PMID 37402592, 2023). "Molecular interactions between NTCP and EGFR are important for supporting viral infection, and point mutations in NTCP and inactivation of EGFR can disrupt the NTCP–EGFR interaction." (PMID 38136637, 2023). "Signaling pathways activated by the epidermal growth factor receptor (EGFR) play an important role in cell proliferation, apoptosis and viral infection." (PMID 38029193, 2023). "Having explored the pivotal role of EGFR in diverse viral infections, we suggest that the growing emphasis on its significance positions EGFR as a promising candidate for future antiviral development." (PMID 38136637, 2023). "Due to a more potent inhibition on EGFR activation by MEKi when compared with EGFR specific inhibitor, the EGFR inhibitor provided additional evidence of the importance of EGFR–MAPK axis in a viral infection." (PMID 37402592, 2023). "EGFR is not only important for understanding diseases related to cell survival and proliferation but also plays a crucial role in understanding viral infections." (PMID 38139259, 2023). "Repressed DENV replication was observed in human monocytes in utilizing the EGFR-specific inhibitor gefitinib, which demonstrates a positive correlation between activated EGFR and viral infection." (PMID 35847084, 2022). "It has been widely reported that EGFR participates in the regulation of host innate immunity during viral infection." (PMID 35847084, 2022). "Together with the knowledge of the roles of EGFR in virus infection, the work presented here revealed the mechanism of how JEV exploits EGFR signaling to prompt virus replication, which is likely to provide insights into JEV-induced CNS invasion." (PMID 35847084, 2022).
viral infection (continued). "Other roles of ASGR1 such as hepatitis C virus binding allowing viral infection or metastasis promotion by interaction with lectins in the tumor microenvironment through the EGFR-ERK pathway are also described in relation with HCC induction." (PMID 36518850, 2022). "This implicated the mediating role of p-EGFR(Tyr1068) in enhancing cellular anti-oxidant ability in response to CAP treatment and/or virus infection." (PMID 35637956, 2022). "The activation of EGFR and its downstream cascade are also essential in restricting the host's innate immunity against virus infection." (PMID 35847084, 2022). "The data showed that exosome-delivered epidermal growth factor receptor (EGFR) reduced INFβ expression in macrophages after viral infection." (PMID 35320943, 2022). "The viral infection was drastically reduced in EGFR-KO cells both in RNA and protein levels in a time-dependent manner compared to that observed in wild-type (WT) hBMECs." (PMID 35847084, 2022). "As previously reported, the phosphorylation of ERK or signal transducers and activators of transcription 3 (STAT3) signaling was downstream of EGFR cascade to virus infection." (PMID 35847084, 2022). "In recent years, the activated EGFR also appeared in response to viral infection, including IAV, PEDV, ZIKV, and severe acute respiratory syndrome coronavirus 2 (SARS-CoV-2)." (PMID 35847084, 2022). "The observed gene expression pattern induced by RNase3 is characteristic of both EGFR- and IFN-associated pathways, which can participate in the macrophage response to bacterial and viral infection, respectively." (PMID 33226440, 2021). "As with primary infection, EGFR signaling is also an important cellular receptor controlling this aspect of the viral infection process." (PMID 34025614, 2021). "The production of both type I and III IFN mRNA levels also corresponded to the production of mRNA levels for the interferon stimulated gene viperin, with significantly lowered mRNA levels seen in cells treated with the EGFR inhibitor prior to viral infection." (PMID 34262037, 2021). "We will conclude by discussing the emerging role of EGFR signaling in innate immunity to viral infections, and how viral evasion mechanisms are contributing to our understanding of fundamental EGFR biology." (PMID 35083168, 2021). "Historically virologists have focused on the canonical pathway regulating the trafficking of ligand-activated EGFRs from the plasma membrane to lysosomes as a roadmap for discovering the role of EGFR during virus infections." (PMID 35083168, 2021). "It is observed that during viral infection through respiratory viruses, EGFR gets activated via the NADPH oxidase signaling pathway in the airway epithelium." (PMID 34093642, 2021). "The purpose of this review is to summarize the multifaceted roles of the epidermal growth factor receptor (EGFR1) in the pathogenesis of viral infections." (PMID 35083168, 2021). "Viral infection per se also activates EGFR and EGFR signaling to ERK1/2, while STATs control the severity of HRV mediated airway inflammation." (PMID 32655557, 2020). "As expected, the activation of EGFR induced by virus infection at 24 hpi was significantly blocked by 10 μM Gefitinib." (PMID 32846937, 2020). "In line with this recognized paradigm, we found that virus infection activated PLC-γ1 partially through EGFR, as treatment with the EGFR specific inhibitor Gefitinib led to a significant inhibition of PLC-γ1 phosphorylation in virus-infected cells." (PMID 32846937, 2020). "To further our understanding of the role of EGFR signaling during virus infection, we performed a time-of-addition assay, and found that post-entry stages were also affected by the EGFR-specific inhibitor Gefitinib during infection of A549 cells." (PMID 32846937, 2020).
viral infection (continued). "Pathway analysis shows their possible participation in viral infection strategies (viral translation), as well as oncogenesis (Wnt and EGFR signalling pathways)." (PMID 31416416, 2019). "This suggests that EGFR signaling is required in the early stages of virus infection, most likely promoting virus endocytosis, which is in turn required for endosomal tubulation." (PMID 31192164, 2019). "For example, in the context of viral infection, hepatitis C virus increases signaling by disrupting EGFR recycling to enhance its surface expression." (PMID 30108171, 2018). "We highlight a novel role for SOCS5 in the regulation of PI3K signaling and demonstrate that SOCS5 primarily protects against viral infection by inhibiting EGFR activity." (PMID 28195529, 2017). "To further determine if WZ4002-resistant cells depend on EGFR signaling for growth, we silenced the EGFR gene by lenti-viral infection of EGFR shRNA." (PMID 26980747, 2016). "All three viral infections showed a statistically significant decrease in the total EGFR relative to the mock control, reflecting the infection-mediated transcriptional downregulation of EGFR." (PMID 27218650, 2016). "Activated EGFR (pY1068) was detected predominantly in the juxtanuclear compartment irrespective of the serum-starved or–fed state, suggesting that viral infection sequesters and sustains EGFR activity even under serum stress." (PMID 27218650, 2016). "We next asked if pUL135 and pUL138 affected cell surface levels of EGFR when expressed outside the context of viral infection." (PMID 27218650, 2016). "The responses that are induced by ligand binding to EGFR, including cell signaling activation, protein kinase phosphorylation, and cytoskeletal network rearrangement, resemble those induced by virus infection." (PMID 26322025, 2015). "Noteworthy, also bile acids were demonstrated to play a role in EGFR activation during viral infection." (PMID 26729094, 2015). "The difference in the expression reached significance only at day 56 because the viral infection per se steeply decreased EGFR expression." (PMID 26322025, 2015). "The function of EGFR was studied in a number of bacterial and viral infections (e.g., C. pneumoniae, Pseudomonas aeruginosa, Neisseria gonorrhoeae, HPV); however, it has not been thoroughly investigated in relation to C. trachomatis pathogenesis." (PMID 25471819, 2014). "The results showed that only when EGFR was inhibited at early stages during virus infection, progeny virus titers were significantly reduced." (PMID 20844577, 2010). "Previous studies have shown that VGF, which is secreted early during infection, induces continuous activation of the EGFR signalling throughout the virus infection cycle as a consequence of its lower affinity for the receptor." (PMID 19388902, 2009). "While reports on Netrin signaling during viral infections are limited, a previous study demonstrated mutual amplification between Netrin-1 and hepatitis C virus via epidermal growth factor receptor pathways, indicating that Netrins can be co-opted during viral pathogenesis." (PMID 40723441, 2025). "Notably, the significant increase in ISGs caused by TOB1 deficiency is the main factor in inhibiting viral infection in IBRS-2 cells, while TOB1 deletion inhibiting FMDV infection via the EGFR pathway, is common in IBRS-2, PK-15, and iPAM cells." (PMID 38512977, 2024). "Taken together, our findings provide novel insight into SARS-CoV-2-induced alterations in mitochondrial dynamics and EGFR trafficking during the early stage of viral infection and their roles in robust SARS-CoV-2 propagation, suggesting that EGFR is an attractive host target for combating COVID-19." (PMID 38734691, 2024). "EGFR might play a role in the overall downregulation of interferon pathways, since virus-activated EGFR has also been shown to suppress IFN signaling during viral infection, thereby decreasing antiviral defense." (PMID 39521937, 2024).